ABCA1 (ATP binding cassette subfamily A member 1)
Diseases named in the same sentence as ABCA1 in open-access papers (continued):
Sharing a sentence is not in itself a finding about the gene and the disease.
hepatoma (25 papers, 2009 to 2026). "Such as, ABCC5 has been associated with immune infiltration and immune cell differentiation in hepatocellular carcinoma, while ABCA1 deletion has been linked to increased inflammatory cell death." (PMID 40445912, 2025). "We examined if ABCA1 expression levels are modulated by HBV-miR-3 in hepatoma cells expressing HBV-miR-3." (PMID 40701520, 2025). "It has been reported to reduce the mRNA and protein levels of MDR1 in human hepatocellular carcinoma cell line HepG2 by down-regulating the human ABCA1 gene involved in multiple transcription factors, such as FOXO1." (PMID 40284452, 2025). "It was also reported that ABCA1 mediates cellular secretion of α-Toc because hepatic α-Toc secretion is suppressed by ABCA1-RNAi or probucol (inactivator of ABCA1) in a rat hepatoma cell line and C57BL/6Cr mice in vivo." (PMID 33920342, 2021). "Analysis of cancer databases showed that ABCA1 expression was lower in colon, breast and liver carcinomas comparing with normal tissues." (PMID 33224889, 2020). "On the other hand, we found that inhibition of EH activity by AUDA increased the protein expression of ABCA1 and promoted cholesterol efflux, leading to a decrease in OA‐induced lipid accumulation in Huh7 hepatoma cells." (PMID 31436906, 2019). "The effect of H2S on ABCA1 expression and lipid metabolism were assessed in vitro by cultured human hepatoma cell line HepG2, and in vivo by ApoE−/− mice with a high-cholesterol diet." (PMID 27136542, 2016). "In hepatoma cells, statins induced ABCA1 expression resulting in cholesterol and phospholipid efflux to apoA-I." (PMID 20025763, 2009). "In addition, we used wet lab experiments to prove that ABCA1 plays a pro-oncogenic role in hepatocellular carcinoma cells by promoting proliferation, invasion, migration, and reducing apoptosis." (PMID 39749197, 2024). "Moreover, adiponectin has been described to increase both mRNA and protein levels of ABCA1 in HepG2 hepatocellular carcinoma cells." (PMID 35273510, 2022). "Interestingly, we also detected a significant increase of ABCA1 protein in human hepatoma cells subjected to USF1 knock-down (HuH7)." (PMID 30545366, 2018). "More in-depth cholesterol-transport and membrane re-organization studies in macrophage or hepatocyte/hepatoma cell lines warrant further investigation and can provide sharper insight as to how these mutant SR-BI receptors behave when all efflux machinery (i.e. ABCA1 and ABCG1) is present." (PMID 23029167, 2012). "Knockdown of SMG1 in HepG2, a hepatocellular carcinoma cell line, resulted in similar increases in MVA pathway genes and in ABCA1, though to a lesser extent." (PMID 35805027, 2022). "To investigate a putative link between hepatic ER stress and HDL levels, we examined the expression of ABCA1, which is crucial in HDL biogenesis, in human HepG2 hepatoma cells after induction of acute ER stress." (PMID 24179149, 2014). "In the human hepatoma cell line HepG2, but not in PMs, the long form of Pim1 (Pim1L) interacts with cell-surface-resident ABCA1 (csABCA1), thereby protecting it from ubiquitination and subsequent lysosomal degradation via its phosphorylation function." (PMID 40526435, 2025). "In contrast, sterols repress ABCA1 transcription in rat hepatoma cells, and cholesterol feeding does not induce ABCA1 expression in parenchymal liver cells." (PMID 24179149, 2014). "However, overexpression, induction, downregulation, inhibition, and knockdown of ABCA1 in human hepatoma Huh7 cells did not decrease SM efflux." (PMID 36007616, 2022). "However, overexpression, induction, downregulation, inhibition, and KD of ABCA1, a well-characterized cholesterol and phospholipid transporter, in human hepatoma Huh7 cells does not decrease SM efflux to HDL." (PMID 36007616, 2022).
Insulin resistance (23 papers, 2006 to 2025). Increased resistance towards insulin, that is, diminished effectiveness of insulin in reducing blood glucose levels. "Stearoyl-CoA desaturase-1 that catalyses oleic acid synthesis and is associated with insulin resistance was increased in visceral adipose tissue and cholesterol efflux components (ABCA1, apoE) were decreased in subcutaneous and liver tissue." (PMID 27488580, 2016). "Although several lines of evidence both in human studies and animal models indicate that ABCA1 plays a role in insulin secretion and insulin resistance, the role of ABCA1 gene variation in T2D susceptibility and insulin resistance is not fully understood." (PMID 26579206, 2015). "Insulin resistance is associated with dysregulation of lipid metabolism and cellular cholesterol homeostasis, and improvement in insulin resistance caused by weight loss in obese individuals was associated with changes in ABCA1 and IDOL/MYLIP in monocytes." (PMID 37094639, 2023). "Being a cholesterol transporter affecting intracellular cholesterol concentrations and cholesterol membrane distribution, ABCA1 is thus expected to play a critical role in islet cholesterol homeostasis, β-cell function, insulin resistance and T2D." (PMID 33562440, 2021). "A decrease in the functional activity of ABCA1 in skeletal muscles contributes to the abnormal accumulation of cholesterol and a decrease in glucose transport under conditions of insulin resistance." (PMID 34201488, 2021). "The fat accumulation was primarily triglycerides, with increased Vldlr expression in STAT and diminished ABCA1 in mice with insulin resistance." (PMID 27124954, 2016). "When the data were analyzed by outcome rather than treatment group, expression of the cholesterol efflux regulator Abca1 was lower in mice that had more insulin resistance (p <0.05)." (PMID 27124954, 2016). "Furthermore, JLD activates AMPK to protect β-cells and stimulates the PPARα/ABCA1 pathway, thereby improving glucose–lipid metabolism, reducing hepatic lipid deposition, and alleviating insulin resistance." (PMID 41334442, 2025). "Additionally, studies in muscle cell, hepatocyte and adipocyte-specific KO models, and some studies in humans, have shown ABCA1 also plays a role in peripheral insulin resistance." (PMID 33562440, 2021). "Carriers of loss-of-function mutations in ABCA1 exhibit impaired insulin secretion without insulin resistance." (PMID 29439145, 2018). "Further, it was reported that a loss-of-function mutation in ABCA1 reduced insulin secretory capacity without affecting insulin resistance in humans." (PMID 26881755, 2016). "In addition, insulin may reduce ABCA1 expression levels in adipocytes, resulting in insulin resistance." (PMID 34975757, 2021). "It is also possible that, in the setting of insulin resistance, hyperinsulinemia interrupts HDL biogenesis via promoting phosphorylation and degradation of ABCA1." (PMID 25925168, 2015). "Thus, decreased expression of ABCG1, ABCA1, and ACSL3 could impair insulin secretion and lead to insulin resistance." (PMID 32612641, 2020). "Defective ABCA1 mediating the efflux of cellular free cholesterol, defective LCAT activity, or increased selective delivery of HDL cholesteryl ester to hepatocytes may be involved in the low HDL levels present with severe insulin resistance." (PMID 30049949, 2018). "The lacking effects of insulin resistance on ABCA1 expression was shown previously also for humans." (PMID 26034989, 2015). "Additionally, models where homeostatic model assessment (HOMA) index score (as a marker for insulin resistance) was forced were evaluated, but resulted in more poorly fitted models, indicating that HAE and ABCA1-specific CEC are independent of insulin resistance and glucose tolerance status." (PMID 28767713, 2017).
ovarian carcinoma (21 papers, 2015 to 2025). A malignant neoplasm originating from the surface ovarian epithelium. "ABCA1 has been associated with the development of acquired chemotherapy resistance and the prediction of adverse outcomes in ovarian cancer patients, indicating the potential role of ABCA1 in cancer treatment." (PMID 40297807, 2025). "Both the overexpression and the downregulation of ABCA1 have been associated with tumorigenesis including ovarian cancer." (PMID 35582032, 2021). "Increased ABCA1 mRNA/protein expression was found to be associated with poor clinical outcome in bowel and ovarian cancer." (PMID 35582032, 2021). "Our study found that high ABCA1 mRNA and protein expression was significantly associated with poor clinical outcome and increased in ovarian cancer cell lines and primary serous ovarian cancer cells following acquired chemotherapy resistance." (PMID 35582032, 2021). "According to our gene dependency network, the mutual information of ABAC1 to prognostic risk of ovarian cancer patients is dependent on BRCA1 (The p-value of the edge from BRCA1 to ABCA1 is 0.045)." (PMID 28615526, 2017). "To further investigate the association between expression of ABCA1 and survival of ovarian cancer patients, we performed tissue microarray on a different cohort containing 55 ovarian patient samples." (PMID 25628764, 2015). "Taken together, methylation of ABCA1 is partially associated with poor prognosis in ovarian cancer patients." (PMID 25628764, 2015). "Result from tissue microarray and TCGA ovarian cancer RNA-Seq dataset also demonstrated that ovarian cancer patients with lower ABCA1 expression were associated with shorter survival." (PMID 25628764, 2015). "Further analysis demonstrated that ABCA1 methylation was associated with poor prognosis in ovarian cancer patients." (PMID 25628764, 2015). "Ovarian cancer patients with higher methylation and lower expression of ABCA1 were associated with shorter survival." (PMID 25628764, 2015). "Furthermore, increased expression of ABCA1 is associated with the development of acquired chemotherapy resistance and poor patient outcome in ovarian cancer." (PMID 37324492, 2023). "Moreover, while ABCA1 expression is closely associated with ovarian cancer invasion and migration, it exhibits anti-cancer effects in prostate cancer." (PMID 37874419, 2023). "In addition, hypermethylation of the ABCA1 promoter was associated with prognosis in ovarian cancer patients." (PMID 33066132, 2020). "Importantly, ovarian cancer patients with higher ABCA1 methylation were associated with shorter survival." (PMID 25628764, 2015). "Furthermore, tissue microarray using 55 ovarian cancer patient samples revealed that patients with a lower level of ABCA1 expression are associated with shorter progress-free survival (P = 0.038)." (PMID 25628764, 2015). "Similarly, analysis of TCGA ovarian cancer RNA-Seq dataset also found that patients with lower expression of ABCA1 are associated with shorter overall survival." (PMID 25628764, 2015). "Interestingly, methylation of ABCA1 is also associated with poor patient outcome in ovarian cancer (OS: hazard ratio: 1.106, P = 0.033; PFS: hazard ratio: 1.096, P = 0.013)." (PMID 25628764, 2015). "A similar phenomenon was observed in a mouse model of ovarian cancer, wherein the cholesterol efflux mediated by ABCA1 upregulation promoted the transition of macrophages to M2 macrophages." (PMID 37874419, 2023). "Likewise, in epithelial ovarian cancer, elevated ABCA1 expression associates with poor clinical outcome and ABCA1 suppression significantly reduces the growth, motility and colony formation of epithelial ovarian cancer cell lines and the size of epithelial ovarian cancer spheroids." (PMID 36439249, 2022). "ABCA1 mRNA and protein levels were significantly increased in ovarian cancer cell lines (OVCAR-5 CBPR and CaOV3 CBPR) with acquired carboplatin resistance." (PMID 35582032, 2021).
ovarian carcinoma (continued). "In our study, we found that apabetalone treatment also reduced ABCA1 protein expression and increased the sensitivity of ovarian cancer cell lines to carboplatin." (PMID 35582032, 2021). "In conclusion, we provided evidence for the role of ABCA1 in ovarian cancer acquired carboplatin resistance and progression." (PMID 35582032, 2021). "Developing strategies to inhibit ABCA1 expression has potential to overcome chemotherapy resistance and improve ovarian cancer survival." (PMID 35582032, 2021). "High ABCA1 and ABCC2 mRNA were significantly associated with reduced PPS in all ovarian cancer subtypes and HGSOC." (PMID 35582032, 2021). "Further experiments need to be performed to examine the feasibility of using apabetalone and the doses required to reduce ABCA1 expression in in vivo ovarian cancer models." (PMID 35582032, 2021). "By analyzing publicly available microarray data using the Kaplan-Meir online plotter, high ABCA1 and ABCB3 mRNA expressions were significantly associated with reduced PFS in all ovarian cancer subtypes." (PMID 35582032, 2021). "Apabetalone treatment reduced ABCA1 protein expression and increased the sensitivity of both parental and carboplatin-resistant ovarian cancer cells to carboplatin." (PMID 35582032, 2021). "In the same study, the methylation status of the ABCA1 promoter has been determined in tissue samples from 76 ovarian cancer patients." (PMID 33066132, 2020). "Having demonstrated that promoter hypermethylation of ABCA1 can be observed in ovarian cancer cell lines, we then proceeded to examine if such epigenetic event can also be observed in ovarian cancer patient samples." (PMID 25628764, 2015). "As ABCA1 is responsible for cholesterol efflux, we first measured the effect of ABCA1 depletion on the cholesterol level of ovarian cancer cells." (PMID 25628764, 2015). "In the current study, we demonstrated promoter hypermethylation of ABCA1, a cholesterol transporter in ovarian cancer cell lines and patient samples." (PMID 25628764, 2015). "Further analysis of ABCA1 methylation in 76 ovarian cancer patient samples demonstrated that patients with higher ABCA1 methylation are associated with high stage (P = 0.0131) and grade (P = 0.0137)." (PMID 25628764, 2015). "Classified as a member of the ATP-binding cassette (ABC) family, ABCA1 was previously identified by methylated DNA immunoprecipitation microarray (mDIP-Chip) to be methylated in ovarian cancer cell lines, A2780 and CP70." (PMID 25628764, 2015). "To further investigate if ABCA1 methylation was predictive of survival in ovarian cancer patients, we performed Kaplan-Meier survival analyses." (PMID 25628764, 2015). "To confirm our microarray result, we first examined the mRNA expression level of ABCA1 in various ovarian cancer cell lines." (PMID 25628764, 2015). "Interestingly, previous studies revealed that the high expression of ABCA1, APLP2, C3, EPHA2, and EFNA1 were associated with poor prognosis and epithelial ovarian cancer progression." (PMID 39135097, 2024). "In addition, high ABCA1 expression in ovarian cancer is related to poor prognosis and promotes malignant cell phenotypes." (PMID 38385857, 2024). "ABCA1 silencing significantly inhibits the migration and invasion of ovarian cancer cells." (PMID 37874419, 2023). "Compared with other FRGs, ABCA1 may be a tumor suppressor that was methylated after dysregulation of transforming growth factor-β signaling in ovarian cancer, presenting a poor prognosis." (PMID 36276279, 2022). "We investigated whether an inhibitor of ABCA1, apabetalone, could decrease ABCA1 expression in ovarian cancer cell lines and increase their sensitivity to carboplatin." (PMID 35582032, 2021). "Specific knockout of ABCA1 or ABCG1 with the inhibition of cholesterol efflux in TAM effectively reversed the pro-tumorigenic effect of TAM in ovarian cancer, which could be applied to develop a novel therapeutic strategy." (PMID 34820325, 2021).
ovarian carcinoma (continued). "In addition, ABCA1 was upregulated in EPCAM+CD45+ tumor cells derived from ascites of patients with ovarian cancer with aggressive features." (PMID 34820325, 2021). "To confirm this hypothesis, we examined the effect of ABCA1 depletion on the growth of ovarian cancer cells." (PMID 25628764, 2015). "Promoter methylation of ABCA1 was observed in ovarian cancer cell lines and patient samples." (PMID 25628764, 2015). "The tumor suppressor function of ABCA1 in ovarian cancer warrants further investigation." (PMID 25628764, 2015). "Epigenetic alteration of ABCA1 may contribute to the resistance of TGF-β-mediated growth suppression in ovarian cancer cells." (PMID 25628764, 2015). "Taken together, these results suggested that promoter hypermethylation may be responsible for the transcriptional repression of ABCA1 in ovarian cancer." (PMID 25628764, 2015). "Moreover, ABCA1 promoted ovarian cancer drug resistance and tumorigenesis." (PMID 34820325, 2021). "Thus, the roles of ABCA1 in ovarian cancer require further investigation." (PMID 34820325, 2021). "ABCA1 may be a tumor suppressor and is hypermethylated in a subset of ovarian cancer patients." (PMID 25628764, 2015). "Ovarian cancer patients with high RASSF1C methylation (which plays an oncogenic role in cancer cells) and low ABCA1 expression have shorter survival." (PMID 40297807, 2025). "ABCA1 mRNA expression was significantly increased in OVCAR-5 CBPR (~2-fold, P = 0.017) and CaOV3 CBPR (~3-fold, P = 0.007) ovarian cancer cell lines, compared to parental OVCAR-5 and CaOV3 cell lines." (PMID 35582032, 2021). "This study investigated the relationship of the five ABC transporters ABCA1, ABCB1, ABCB3 (also known as TAP2), ABCC2 and ABCG2 with ovarian cancer chemoresistance and outcome." (PMID 35582032, 2021). "This disparate finding may be due to the smaller cohort size, including different ovarian cancer subtypes and a mixture of both low- and high-grade disease, varied chemotherapy treatment, different methods of assessment and the use different antibodies to detect ABCA1." (PMID 35582032, 2021). "Therefore, we hypothesized that ABCA1 might act as a tumor suppressor in ovarian cancer." (PMID 25628764, 2015). "Thus, we hypothesized that ABCA1 may be involved in ovarian cancer and its initiation." (PMID 25628764, 2015). "Our result showed that ABCA1, which is upregulated by TGF-β and is a major regulator of cellular cholesterol, is hypermethylated in a subset of ovarian cancer cell lines." (PMID 25628764, 2015). "We first compared the expression level of ABCA1 in IOSE cells and a panel of ovarian cancer cell lines and found that ABCA1 was expressed in HeyC2, SKOV3, MCP3, and MCP2 ovarian cancer cell lines but downregulated in A2780 and CP70 ovarian cancer cell lines." (PMID 25628764, 2015). "A more recent study investigating drug-resistant tumor cell phenotypes in the ascitic fluid of epithelial ovarian cancer patients identified that a population of cells that were EpCAM+CD45+ were more resistant compared to EpCAM+ tumor cells and overexpressed ABCA1." (PMID 35582032, 2021). "By analyzing three ovarian cancer cell lines, HEY C2, SK-OV-3, and A2780, and three MDR sublines of A2780 selected against cisplatin, A2780/CP70, A2780/MCP2, and A2780/MCP3, ABCA1 has been found to be expressed in A2780/MCP2 and A2780/MCP3 cells but downregulated in A2780 and A2780/CP70 cells." (PMID 33066132, 2020). "Lentiviral knockdown of ABCA1 was performed in MCP3 and HeyC2 ovarian cancer cells." (PMID 25628764, 2015). "One of the genes, ABCA1, which exhibited promoter methylation in a subset of ovarian cancer cell lines but not in IOSE cells, was selected for further analysis." (PMID 25628764, 2015). "Finally, high expression of ABCA1 (and other members of the ABCA family) correlates with reduced survival in serous ovarian cancer patients and siRNA-mediated suppression of ABCA1 inhibited ovarian cancer cell growth and migration in vitro." (PMID 26002572, 2015).